DNAH1 (dynein axonemal heavy chain 1)
Description:
Force generating protein of cilia required for sperm flagellum motility. Produces force towards the minus ends of microtubules. Dynein has ATPase activity; the force-producing power stroke is thought to occur on release of ADP. Required in spermatozoa for the formation of the inner dynein arms and biogenesis of the axoneme.
Synonyms: HSRF-1; DNAHC1; XLHSRF-1; HDHC7; HL-11; HL11; CILD37; SPGF18
Tractability: Small molecule: a structure with a bound ligand is known. Antibody: its Gene Ontology location is reachable by antibodies, with medium confidence. PROTAC: ubiquitination databases record sites on it.
Gene: Protein-coding gene on chromosome 3 (52,316,319 to 52,400,492, forward strand). Ensembl gene ENSG00000114841.
Subcellular location: Cytoplasm, cytoskeleton, cilium axoneme; Cell projection, cilium, flagellum
Gene Ontology:
Molecular function: dynein intermediate chain binding; dynein light intermediate chain binding; microtubule motor activity; minus-end-directed microtubule motor activity; ATP binding
Biological process: flagellated sperm motility; inner dynein arm assembly; sperm axoneme assembly; cilium-dependent cell motility; microtubule-based movement
Cellular component: axoneme; inner dynein arm; sperm flagellum; axonemal dynein complex; dynein complex; motile cilium
Genetic constraint (gnomAD): Loss-of-function variants: 327 observed, 471.83 expected, observed/expected ratio (o/e) 0.69, 90% interval 0.63 to 0.76. The upper end of that interval is the gene's LOEUF score, 0.76, which puts it in group 3 of 6, group 1 being the genes least tolerant of losing a copy. Missense variants: 5,052 observed, 5,581.7 expected, observed/expected ratio (o/e) 0.91, 90% interval 0.88 to 0.93. Synonymous variants: 2,192 observed, 2,203.7 expected, observed/expected ratio (o/e) 0.99, 90% interval 0.96 to 1.03.
Gene-disease validity (ClinGen):
ClinGen rates the evidence that DNAH1 causes each of these diseases.
spermatogenic failure 18 (autosomal recessive): Definitive.
primary ciliary dyskinesia (autosomal recessive): Limited. A rare, genetically heterogeneous, primarily respiratory disorder characterized by chronic upper and lower respiratory tract disease.
Homologues: Orthologues: chimpanzee DNAH1 (99% identical), macaque DNAH1 (98% identical), pig DNAH1 (91% identical), dog DNAH1 (91% identical), guinea pig DNAH1 (90% identical), mouse Dnah1 (89% identical), rabbit DNAH1 (88% identical), rat Dnah1 (87% identical), tropical clawed frog dnah1 (73% identical), zebrafish dnah1 (68% identical), Drosophila melanogaster sac (8% identical). Paralogues in human: DNAH7 (39% identical), DNAH12 (39% identical), DNAH3 (38% identical), DNAH6 (34% identical), DNAH2 (34% identical), DNAH10 (30% identical), DNAH8 (29% identical), DNAH9 (29% identical), DNAH5 (29% identical), DNAH17 (29% identical), DNAH11 (29% identical), DNAH14 (28% identical), and 3 more.
Diseases named in the same sentence as DNAH1 in open-access papers:
DNAH1 is named in the same sentence as 26 diseases in open-access papers, as found by Europe PMC text mining. Sharing a sentence is not in itself a finding about the gene and the disease. The quoted sentences say what the papers report.
male infertility (17 papers, 2015 to 2025). The inability of the male to effect fertilization of an ovum after a specified period of unprotected intercourse. "Deficiency of DNAH12 leads to the failure of DNALI1 and DNAH1 recruitment to sperm flagella, resulting in abnormal sperm morphology characterized by compromised axoneme organization, causing male infertility." (PMID 40146200, 2025). "DNAH1 regulates sperm cilia and flagella function, and mutations cause multiple morphologic abnormalities of the flagella and male infertility due to impaired sperm motility (asthenozoospermia)." (PMID 41222740, 2025). "The polymorphisms in the DNAH1 gene showed the potential association with male infertility in the Chinese33,34, while the variation in the WDR1 gene was the risk factor for gout development in the Chinese population." (PMID 35618720, 2022). "Mutations in DNAH1 can cause morphological abnormalities of the sperm flagella and lead to male infertility." (PMID 36140773, 2022). "Since then, various pathogenic mutations in DNAH1 have been reported in various populations, causing male infertility." (PMID 34867808, 2021). "Physicians should be aware of genetic variants in male infertility patients and DNAH1 mutations should be considered in patients with asthenospermia or azoospermia." (PMID 30544445, 2018). "Physicians should be aware of the possibility of male infertility patients having genetic variants causative of their condition, and DNAH1 mutations in particular should be considered in patients with asthenospermia or azoospermia." (PMID 30544445, 2018). "Mutations of DNAH12 cause male infertility by impairing DNAH1 and DNALI1 recruitment." (PMID 40568142, 2025). "DNAH1 is thus an important candidate for a causative gene of male infertility." (PMID 30544445, 2018). "Mutation of Dnah1 in mice has been reported to cause male infertility, suggesting that it may play an important role in influencing mating behavior." (PMID 26000771, 2015). "Currently, 13 members of the DNAH gene family have been reported, including DNAH1 to DNAH3, DNAH5 to DNAH12, DNAH14, and DNAH17, among which 11 genes (DNAH1, DNAH2, DNAH5 to DNAH12, and DNAH17) are associated with male infertility." (PMID 38312775, 2024). "The DNAH1 gene is involved in the formation of the internal power arm of sperm, and its deletion can lead to decreased sperm motility and male infertility." (PMID 36553607, 2022). "For example, mutations in IDA and ODA genes, such as DNAH1, DNAH2, DNAH8, and DNAH10, cause male infertility due to asthenozoospermia with multiple morphological abnormalities of the sperm flagella." (PMID 36726469, 2022). "In humans, there are 13 dynein axonemal heavy chain (DNAH) proteins (DNAH1–3, DNAH5–12, DNAH14, and DNAH17) and mutations in many of these genes have been associated with male infertility." (PMID 36140773, 2022). "DNAH1 is one of the most important members of the inner dynein arm and is considered an essential candidate gene for male infertility." (PMID 34867808, 2021). "DNAH1, one of several dynein members highly correlated with sperm dysmotility, has been confirmed to be an important candidate gene for male infertility." (PMID 30544445, 2018). "To study the genetic pathogeny of male infertility, we chose 52 genes altogether reported to be related to this condition including DNAH1 as candidate genes by reviewing the literature." (PMID 30544445, 2018). "Additionally, other DNAHs, such as DNAH1, DNAH2, DNAH8, DNAH10, DNAH12, and DNAH17, are suggested to be pathogenic genes of isolated male infertility." (PMID 39503742, 2024). "DNAH1 protein deficiencies may result in ciliary structure and function defects and impair sperm axoneme biogenesis, proposed to result in PCD and male infertility, respectively." (PMID 37457836, 2023).
male infertility (continued). "Except for the DNAH1 gene homozygous missense variant c.3460A>C (p.Lys1154Gln) that was reported to be responsible for PCD in combination with SI, the other known variants were involved in male infertility." (PMID 37457836, 2023). "Previous studies demonstrate pathogenic DNAH1 or DNAH2 variants cause male infertility and MMAF without obvious PCD symptoms." (PMID 33968937, 2021). "Mutations in two IDA heavy-chain protein-encoding genes, DNAH1 (MIM: 603332) and DNAH2 (MIM: 603333), and two ODA heavy chain components, DNAH8 (MIM: 603337) and DNAH17 (MIM: 610063), have been described in individuals with isolated male infertility due to asthenoteratozoospermia." (PMID 37424858, 2023). "Of interest, variants in DNAH1 and DNAH9 genes, reported to be associated with PCD, have been depicted in patients with only male infertility, resulted from asthenozoospermia, without other ciliary disorders." (PMID 35692830, 2022).
Infertility (9 papers, 2018 to 2025). "It has been demonstrated that infertile males with variants in DNAH1, DNAH2, DNAH7, and DNAH8 have a favorable prognosis, while patients with variants in DNAH17 have poor outcomes after ICSI treatment." (PMID 39503742, 2024). "Based on structural analysis, DNALI1 was found to be linked to the C-terminus of DNAH1, and infertile patients with DNAH1 mutations also presented DNALI1 defect in human beings." (PMID 36726469, 2022). "Among Chinese infertile patients, heterozygous mutations in DNAH1 are thus potential causes of the infertility." (PMID 30544445, 2018). "Other dynein family members, DNAH5 and DNAH1, are associated with infertility." (PMID 34199109, 2021). "General information and semen parameters of infertile patients with DNAH1 gene mutations." (PMID 30544445, 2018). "For example, alterations in genes such as SPATA7, DNAH1, DNAI1, and DNAJB11 have been associated with MMAF-related infertility." (PMID 40410177, 2025). "(L) Pedigree of a family with three infertile males, P12 (III-2), P13 (III:6), and P14 (III:8); MT: the DNAH1 mutation c.11275C>T; p.Arg3759Cys." (PMID 40146200, 2025). "In the present study, we discovered several new DNAH1 variations in Chinese male patients with infertility and made a prediction by bioinformatic analysis." (PMID 30544445, 2018). "In Dnah1 mutant mice, abnormal sperm behavior, fertilization failure, and reduced ciliary beat frequency were observed, similar to phenotypes of patients suffering from infertility and PCD." (PMID 37457836, 2023). "We explored 4 novel variations of the DNAH1 gene in Chinese infertile patients." (PMID 30544445, 2018).
asthenozoospermia (8 papers, 2015 to 2025). "Mutation screening of the DNAH1 gene was performed on 87 cases of asthenozoospermia with targeted high-throughput sequencing technology; another 200 nonobstructive azoospermia cases were further analyzed to investigate the prevalence of DNAH1 variations." (PMID 30544445, 2018). "Recently, mutations in DNAH1 have been heavily associated with dysplasia of the sperm fibrous sheet, several flagellar defects and asthenozoospermia in humans." (PMID 29985951, 2018). "Dnah1 knock-out (KO) mice only show motility, but no structural sperm defects (asthenozoospermia), whereas in humans DNAH1 truncating mutations induce a MMAF phenotype." (PMID 31781811, 2020). "Variants in DNAH1 have been reported to cause asthenozoospermia without any accompanying PCD symptoms." (PMID 25927852, 2015).
primary ciliary dyskinesia (6 papers, 2015 to 2024). "In humans, missense or frameshift mutations in DNAH1 have been associated with Primary Ciliary Dyskinesia (PCD)." (PMID 33665191, 2021). "A few DNAH1 genetic variants have been postulated to have a role in the development of BO in patients with primary ciliary dyskinesia (PCD), but there is limited evidence regarding this, and etiologies are uncertain." (PMID 34277212, 2021). "Previous research has noted the association of several other dynein heavy chain-encoding genes, such as DNAH1, DNAH5, DNAH9, and DNAH11, with ciliary primary dyskinesia (PCD) and laterality defects." (PMID 36459505, 2022). "Meanwhile, the DNAH1 gene is also associated with primary ciliary dyskinesia (PCD)." (PMID 35456050, 2022).
Azoospermia (3 papers, 2018 to 2023). Absence of any measurable level of sperm,whereby spermatozoa cannot be observed even after centrifugation of the semen pellet. "Overall, 2.09% of patients were found to carry DNAH1 variations, and another 4 pathogenic variations identified by bioinformatics’ analyses were detected in 3 azoospermia patients (P4–P6)." (PMID 30544445, 2018). "For example, mutation in DNAH1, encoding a component of IDA3, has been linked to azoospermia in patients." (PMID 31383820, 2019).
schizophrenia (3 papers, 2018 to 2025). A major psychotic disorder characterized by abnormalities in the perception or expression of reality. "The mechanisms underlying the influence of ALAS1, DNAH1, and PRKCD on schizophrenia are attributed to their proximity to TSS/TES." (PMID 39905509, 2025). "Among highly ranked genes lacking SFARI Gene scores and OMIM annotations, previous studies suggest association with NDDs and schizophrenia [OBSCN, PLEC, RYR2, ZSWIM8], cortical formation and thickness [LAMA5, GOLGA3), and neurodegenerative diseases (PKHD1, DNAH1]." (PMID 35596027, 2023).
teratozoospermia (3 papers, 2018 to 2022). "DNAH1 gene polymorphisms are highly correlated with astheno-teratozoospermia, but limited information has been reported on pathogenic variations in DNAH1 in the Chinese population." (PMID 30544445, 2018). "In particular, mutations in DNAH1 have been associated in the past with a good pregnancy rate, suggesting that further study is required to identify more variants on dynein genes that might contribute to teratozoospermia and have the potential to improve ART outcome or prognosis." (PMID 36140773, 2022). "Next, we identified in a patient diagnosed with severe astheno-teratozoospermia three heterozygous variations in DNAH1, two transmitted by his mother and one by his father." (PMID 33809228, 2021).
ciliopathy (2 papers, 2017 to 2022). A genetic disorder of the cellular cilia or the cilia anchoring structures, the basal bodies, or of ciliary function. "We also found that 67 HLHS-associated genes, 157 ciliopathy-associated genes and 3 genes associated with both (CCDC65, KIAA0586 and DNAH1) were connected via 841 intermediate interactors." (PMID 35456433, 2022). "Additional heterozygous (non-pathogenic) alleles in known ciliopathy genes were also detected including NPHP3: rs772079066 and DNAH1: rs536088715." (PMID 28973549, 2017).
colorectal cancer (1 paper, 2015). A primary or metastatic malignant neoplasm that affects the colon or rectum. "The DNAH1 mutation has been detected in exome-sequenced colorectal cancer and melanoma specimens." (PMID 25997441, 2015).
Dextrocardia (1 paper, 2021). The heart is located in the right hand sided hemithorax. "It is worth noting that DNAH1:p.Tyr3688Cys (as an example) was found in heterozygous state in a child with dextrocardia; the only other variant reported in the genes of interest in this patient was DNAH6:p.Ile213Val (Condel: 0.00)." (PMID 34768622, 2021).
female infertility (1 paper, 2023). Diminished or absent ability of a female to achieve conception. "We present, for the first time, evidence that DNAH1 variants do not necessarily lead to female infertility." (PMID 37457836, 2023).
Huntington disease (1 paper, 2022). Huntington disease (HD) is a rare neurodegenerative disorder of the central nervous system characterized by unwanted choreatic movements, behavioral and psychiatric disturbances and dementia. "The hub genes in gene set B were DNAI2, DNAI1, DNAH1, DNAH9 and DNALI1, all of which were enriched in Huntington’s disease." (PMID 36577966, 2022).
lung adenocarcinoma (1 paper, 2026). A carcinoma that arises from the lung and is characterized by the presence of malignant glandular epithelial cells. "The transcriptomic data revealed that five genes (CAMK1D, BCAS3, DNAH1, PDE10A, and C18orf63) were differentially expressed between lung adenocarcinoma patients and healthy individuals." (PMID 41868793, 2026).
nasopharyngeal carcinoma (1 paper, 2025). A carcinoma arising from the nasopharyngeal epithelium. "By repositioning through an epigenetic target, alprazolam was found to interact with the “Other” category target DNAH1 (Q9P2D7), which is related to indications such as Pick’s disease and nasopharyngeal carcinoma." (PMID 39860130, 2025).
Situs inversus totalis (1 paper, 2022). "Dynein axonemal heavy chain 17 (DNAH17) is a protein of the DNAH family of which four genes have already been associated with autosomal recessive PCD, situs inversus totalis or heterotaxy, namely DNAH1, DNAH5, DNAH9, and DNAH11." (PMID 35474353, 2022).
squamous cell carcinoma (1 paper, 2015). A carcinoma arising from squamous epithelial cells. "DNAH1 is involved in the significant differences in DNA copy number between adenocarcinoma and squamous cell carcinoma." (PMID 25997441, 2015).
tumours (1 paper, 2021). "Likewise, the following marker genes were selected for analysis in PF tumours: LAMA2, ALDH1L1, SLC6A13, IGSF1, and CXorf67 for PFA; and NELL2, DNAH1, CEP83, C9orf72, and NXNL2 for PFB tumours." (PMID 34314101, 2021).
DNAH1 also shares sentences with these, for which no sentence is quoted: adenocarcinoma (1 paper); breast carcinoma (1); Colon Cancer (1); developmental delay (1); dysplasia of fibrous (1); gout (1); melanoma (1); neurodegenerative disease (1); Pick disease (1).